LAMA4 (laminin subunit alpha 4)
Diseases named in the same sentence as LAMA4 in open-access papers (continued):
Sharing a sentence is not in itself a finding about the gene and the disease.
melanoma (3 papers, 2011 to 2022). A malignant, usually aggressive tumor composed of atypical, neoplastic melanocytes. "We showed melanoma dLNs have relatively higher Lama4 than healthy controls, suggesting that Lama4 is a target for modulating the tumor microenvironment." (PMID 35775481, 2022).
metastatic tumors (3 papers, 2020 to 2024). "We also demonstrated that LAMA4 downregulation resulted in a reduction of CAFs in metastatic tumors in nude mice." (PMID 32929348, 2020). "Moreover, LAMA4[circle112550019-112550510] and LAMA4 mRNA expression were increased in metastatic tumors of individuals with HCC, and LAMA4 expression level was negatively correlated with patient survival time." (PMID 39850493, 2024). "Interestingly, LAMA4 and FOXQ1 have been identified as molecular determinants of metastatic tumor re-initiation in breast cancer." (PMID 36319643, 2022). "We compared mRNA level of LAMA4 between primary tumors and non-matched metastatic tumors using the ICGC database." (PMID 32929348, 2020).
triple-negative breast carcinoma (3 papers, 2018 to 2021). An invasive breast carcinoma which is negative for expression of estrogen receptor (ER), progesterone receptor (PR), and human epidermal growth factor receptor 2 (HER2). "Specifically, in basal-like triple negative breast carcinoma cells, the levels of both LAMA4 mRNA and laminin-α4 are elevated when compared to that in adjacent normal tissue samples." (PMID 31781574, 2019). "LAMA4 mRNA and protein expression was shown to be elevated in triple-negative breast cancer." (PMID 34414238, 2021). "While it is tempting to speculate that strict cell type specificity of observed phenomenon may inform future therapy for triple negative breast cancer, detailed studies of SORC2/LAMA4 relationship are warranted." (PMID 31781574, 2019).
clear cell renal carcinoma (2 papers, 2021 to 2022). A malignant epithelial neoplasm of the kidney characterized by the presence of lipid-containing clear cells within a vascular network. "The finding that LAMA4, BIRC7, GALNTL6, WNK2, and IGFBP2 are potential targets of miR-217 at different times of tumor evolution may help to develop stage-specific strategies, taking into account the differential expression of miR-217 in each stage of clear cell renal carcinoma progression." (PMID 35936681, 2022).
heart failure (2 papers, 2018 to 2019). Inability of the heart to pump blood at an adequate rate to meet tissue metabolic requirements. "Patient 62 (PRKAG2: c.1589A>G, p.His530Arg; LAMA4: c.241C>T p.Pro81Ser) was 26 years old and had suffered from heart failure for 2 years." (PMID 30165862, 2018).
maturity onset diabetes (2 papers, 2023 to 2024). "The biological function of the putative effector genes NUS1 and LAMA4 as well as the result of the enrichment analysis highlight adipogenesis and cholesterol trafficking as potential biological mechanisms influencing the comorbidity between type 2 diabetes and schizophrenia." (PMID 38383672, 2024). "Of these, we defined 15 genes showing evidence of involvement in both type 2 diabetes and schizophrenia with a total score of at least three, and three putative effector genes that displayed at least four different lines of evidence, namely EGR2, LAMA4 and NUS1." (PMID 38383672, 2024).
osteoarthritis (2 papers, 2019 to 2023). A noninflammatory degenerative joint disease occurring chiefly in older persons, characterized by degeneration of the articular cartilage, hypertrophy of bone at the margins and changes in the synovial membrane. "Alternatively, six of the top concordant genes (HTR7, TRAK1, LAMA4, HS6ST1, PDE4A, GPNMB) at 52 weeks have been documented in prior osteoarthritis literature." (PMID 37134114, 2023). "ADAMTS5 has a direct connection with Osteoarthritis pathway while LAMA4 is not." (PMID 34970658, 2019).
schizophrenia (2 papers, 2016 to 2024). A major psychotic disorder characterized by abnormalities in the perception or expression of reality. "LAMA4 shows differential expression in pancreatic islets from healthy versus diabetes patients and in brains from schizophrenia patients versus controls." (PMID 38383672, 2024).
African trypanosomiasis (1 paper, 2022). "PBS and CLR test approaches have both indicated PSGs including IL12A, LAMA4, MYD88, SPAST and BOLA to confer resistance mechanisms towards the African trypanosomiasis and tick infestation." (PMID 35428239, 2022).
Alport syndrome (1 paper, 2022). A rare renal disease characterized by glomerular nephropathy with hematuria progressing to end-stage renal disease (ESRD), frequently associated with sensorineural deafness, and occasionally with ocular anomalies. "For instance, in Alport’s syndrome, mutations in Lama4, Lama5, or collagen IV genes disrupt or enlarge basement membrane pores leading to severe leakage of plasma proteins into the urine, known as proteinuria." (PMID 36073544, 2022).
amoebiasis (1 paper, 2022). "For example, among amoebiasis pathway-related proteins, integrin beta-2 (ITGB2), heat shock protein beta-1 (HSPB1), LCN2, leukocyte elastase inhibitor (SERPINB1), laminin subunit alpha-4 (LAMA4), and fibronectin (FN1) have been found to be correlated with immunity." (PMID 36387401, 2022).
benign prostatic hyperplasia (1 paper, 2019). A non-cancerous nodular enlargement of the prostate gland. "LAMA4 (Laminin subunit alpha 4): LAMA4 is consistently upregulated in benign prostatic hyperplasia when compared to normal prostate tissues." (PMID 34290571, 2019).
Cirrhosis (1 paper, 2024). A chronic disorder of the liver in which liver tissue becomes scarred and is partially replaced by regenerative nodules and fibrotic tissue resulting in loss of liver function. "In conclusion, this study revealed the expression profile of eccDNA in HBV-related liver cancer and cirrhosis, ultimately identifying the target genes LAMA4[circle112550019-112550510] and KANK1[circle674459-674907]." (PMID 39850493, 2024).
colorectal tumors (1 paper, 2018). "High LAMA4/LAMA5 ratio is associated with increased permeability of basement membranes suggesting that basement membranes produced by colorectal tumors might be an important hindrance to their own dissemination in patients." (PMID 29504916, 2018).
COVID-19 (1 paper, 2024). A disease caused by infection with severe acute respiratory syndrome coronavirus 2. "Compared with the control data, LAMA4 and VEGFC were highly expressed in children with myocarditis and COVID-19, whereas APOE and TNFRSF9 were expressed at low levels." (PMID 39026189, 2024).
fibrosis (1 paper, 2025). the formation of excess fibrous connective tissue in an organ or tissue in a reparative or reactive process. "CCDC80, LAMA4, PDGFRB, PODN, and SPARC are potential mediators of intestinal fibrosis due to common expression among ileal and colonic strictures." (PMID 40398622, 2025).
gastric adenocarcinoma (1 paper, 2023). "We found that LAMA4 was increased during the progression of gastric adenocarcinoma, and its overexpression significantly correlated with poor overall survival of GAC patients, consistent with a previous report." (PMID 36520032, 2023).
genitourinary neoplasms (1 paper, 2024). "LAMA4 is a cancer-treatment target and high expression of LAMA4 is associated with various malignant tumors such as hematologic neoplasm, digestive system neoplasms and genitourinary neoplasms." (PMID 37694778, 2024).
hemorrhagic disease (1 paper, 2023). Spontaneous or near spontaneous bleeding caused by a defect in clotting mechanisms (blood coagulation disorders) or another abnormality causing a structural flaw in the blood vessels (hemostatic disorders). "Global Lama4-KO mice develop hemorrhagic disease during the embryonic and neonatal periods, with extensive bleeding and deterioration of microvessel growth." (PMID 37092548, 2023).
Hirschsprung disease (1 paper, 2025). Hirschsprung disease (HSCR) is a congenital intestinal motility disorder that is characterized by signs of intestinal obstruction due to the presence of an aganglionic segment of variable extent in the terminal part of the colon. "Of these genes, LAMA4, ZEB2, CTNNAL1, ITGA6 and ITIH5 have previously been associated with Hirschsprung’s disease and ZEB2 was shown to genetically interact with SOX10." (PMID 39982575, 2025).
lipodystrophy (1 paper, 2014). A congenital or acquired disorder characterized by abnormal loss or redistribution of the adipose tissue in the body. "The livers of the Lama4−/− mice on standard diet did not display signs of liver steatosis after 40 weeks suggesting that the decreased body fat in Lama4−/− mice does not represent a form of lipodystrophy." (PMID 25310607, 2014).
liver cancer (1 paper, 2024). An epithelial or non-epithelial malignant neoplasm that arises from the liver. "Kaplan–Meier survival analysis results of data derived from TCGA and GSE7642 (a subset of liver cancer in the GEO database) indicated that high LAMA4 expression is associated with the survival of patients with HCC with short-term correlation." (PMID 39850493, 2024). "Experiments have verified that LAMA4[circle112550019-112550510] and KANK1[circle674459-674907] are real and expressed target genes, and their source genes are closely related to the survival time of patients with liver cancer." (PMID 39850493, 2024).
osteoporosis (1 paper, 2025). A condition of reduced bone mass, with decreased cortical thickness and a decrease in the number and size of the trabeculae of cancellous bone (but normal chemical composition), resulting in increased fracture incidence. "The elevation in LAMA4 is thought to be a compensatory response due to the accumulation of fat droplets, which is significant in the context of disuse osteoporosis development." (PMID 40130165, 2025). "Identifying 8 key genes as potential regulatory target genes for the differentiation of mesenchymal stem cells into osteoblasts or adipocytes under the condition of disuse osteoporosis (ITGB3, LAMC1, COL6A3, ITGA8, PDGFRB, ITGA4, LAMB1, LAMA4)." (PMID 40130165, 2025).
osteosarcoma (1 paper, 2022). A usually aggressive malignant bone-forming mesenchymal neoplasm, predominantly affecting adolescents and young adults. "In osteosarcoma, we first reported that LAMA4 was upregulated in osteosarcoma and promoted proliferation and migration in MNNG/HOS and 143B cells." (PMID 36539799, 2022). "To investigate this possibility, we first analysed the expression of LAMA4 from the TNMplot database and found that LAMA4 was significantly upregulated in osteosarcoma compared with normal tissues." (PMID 36539799, 2022). "To further evaluate the role of LAMA4 in osteosarcoma, we then knocked down LAMA4 in MNNG/HOS and 143B cells." (PMID 36539799, 2022). "In addition, we also found that KLF4 upregulated LAMA4 expression by directly binding to its promoter and that LINC00629 inhibited ER stress-induced apoptosis and facilitated osteosarcoma cell clonogenicity and metastasis by activating the KLF4-LAMA4 pathway." (PMID 36539799, 2022). "To determine whether LINC00629 elevates the osteosarcoma cell adaption to ER stress and facilitates tumorigenesis by regulating the KLF4-LAMA4 axis, we first overexpressed LINC00629 in KLF4- or LAMA4-depleted MNNG/HOS cells and these cells were treated with 3 μM TM for 36 h." (PMID 36539799, 2022).
preeclampsia (1 paper, 2025). Preeclampsia is a hypertensive disorder of pregnancy that is characterized by new-onset hypertension with proteinuria presenting after 20 weeks of gestation, and depending on mild or severe forms may initially present with severe headache, visual disturbances, and hyperreflexia. "Previous studies have shown that LAMA4 is implicated in regulating the onset and progression of preeclampsia." (PMID 40625359, 2025).
prostate carcinoma (1 paper, 2019). A carcinoma that arises from epithelial cells of the prostate gland. "Elevated level of LAMA4 expression as well as two other chains of laminin 411 is observed in metastatic lymph nodes of prostate cancer patients in comparison with metastasis-free lymph nodes." (PMID 31781574, 2019).
psoriasis (1 paper, 2018). An autoimmune condition characterized by red, well-delineated plaques with silvery scales that are usually on the extensor surfaces and scalp. "Several genes reported to be involved in psoriasis pathogenesis including S100A9, S100A8, PTPN22, PTPN6, LAMA4, IL1B and IL12RA were involved in many of these enriched biological processes." (PMID 30092825, 2018).
renal fibrosis (1 paper, 2023). A final common manifestation of a wide variety of chronic kidney diseases characterized by glomerulosclerosis and tubulointerstitial fibrosis. "Correspondingly, LAMA4-deficiency has been linked to cardiac and renal fibrosis." (PMID 36912952, 2023).
SAPHO syndrome (1 paper, 2019). SAPHO syndrome (acronym for Synovitis, Acne, Pustulosis, Hyperostosis and Osteitis) is an auto-inflammatory disease, mainly characterized by the association of neutrophilic cutaneous involvement and chronic osteomyelitis. "Components of laminin (LAMA4, LAMB1 and LAMC1) and MCAM also help cell adhesion and slow-rolling of neutrophils, the up-regulation of whom indicated excessive neutrophil activation and migration in SAPHO syndrome." (PMID 31395074, 2019).
steatosis (1 paper, 2014). Increased lipid within the cytoplasm of cells. "On a high-fat diet Lama4−/− mice only had very mild steatosis." (PMID 25310607, 2014).
stricture (1 paper, 2025). "Coiled-coil domain-containing 80 (CCDC80) and laminin subunit alpha 4 (LAMA4) are common among pediatric ileal and adult colonic strictures." (PMID 40398622, 2025).
teratoma (1 paper, 2020). A non-seminomatous germ cell tumor characterized by the presence of various tissues which correspond to the different germinal layers (endoderm, mesoderm, and ectoderm). "Lama4 expression was on the same level in both types of teratomas, whereas Lama5 and Lamb2 expression was significantly lower in Pax7−/− teratomas." (PMID 32552916, 2020).
tumor (57 papers, 2008 to 2026). "Among them, the Wnt/ß-catenin pathway (p = 0.02, z-score: 0.53), previously implicated in LAMA4 induction in tumor endothelium, was activated." (PMID 35267534, 2022). "The association between LAMA4 and infiltration of immune cells was explored using Tumor Immune Estimation Resource (TIMER) and GEPIA." (PMID 34414238, 2021). "LAMA4 is distinct from other laminin isoforms in that it lacks a polymerization domain with the loss of this domain potentially facilitating tumor cell migration." (PMID 32571313, 2020). "Furthermore, LAMA4 expression was significantly associated with markers of M2 and tumor-associated macrophages (TAMs)." (PMID 34414238, 2021). "Interestingly, LAMA4 was recently described as an “oncolaminin” due to its strong association with cancer cell migration and tumor progression in a range of cancers." (PMID 32571313, 2020). "Additionally, we further characterized two ECM-associated factors, PDPN and LAMA4, and found that their expression was largely limited to tumor cells in HSA tissue." (PMID 32571313, 2020). "Furthermore, LAMA4 expression was positively correlated with tumor severity and in silico analyses revealed that LAMA4 was associated with altered tumor microenvironment." (PMID 32929348, 2020). "Since LAMA4 is associated with tumor aggressiveness, LAMA4 activity in cancer cells might counteract the anti-tumor effect associated with enhanced TIL entry." (PMID 33250894, 2020). "Tumor-secreted LAMA4 engaged macrophage surface receptor ITGA6 to trigger GATA3 activation and reprogram macrophages toward a pro-metastatic and immunosuppressive phenotype." (PMID 41610310, 2026). "In orthotopic lung metastasis models, FOXC2+ tumor cells leveraged LAMA4 to reshape the pulmonary metastatic niche, thereby reinforcing distant metastatic dissemination." (PMID 41610310, 2026). "We explored the expression dynamics of LAMA4 in the tumor microenvironment (TME) by analyzing single-cell RNA sequencing data from GSE168652." (PMID 40881886, 2025). "In vivo, METTL16 overexpression induces tumor growth, increases LAMA4 and COL4A1 expression, and enhances cisplatin resistance." (PMID 41322419, 2025). "SPON1 was more diffusely upregulated in grade II tumor and infiltrating multiple stromal cell types, while LAMA4 was enriched in tumor ECs in grade III samples." (PMID 41366031, 2025). "KLF4 also directly combines with the promoter of its downstream gene, laminin subunit alpha 4 (LAMA4), to boost its transcription, thus suppressing apoptosis of OS cells and facilitating tumour occurrence and migration." (PMID 38546623, 2024). "LAMA‐4 inhibits tumor cell migration and growth along blood vessels and is thus an important target for tumor cell invasion and angiogenesis." (PMID 39440923, 2024). "We analyzed the significantly upregulated genes in TDECs related to tumor growth factors and selected Angpt2, Lama4, Egr1, Egr3, and Vegfa." (PMID 39440923, 2024). "Considering that LAMA4 is closely related to the migration of cancer cells and tumor progression in a series of tumors, the latest research describes LAMA4 as “oncolaminin.”17 The crosstalk between Notch and TGF-β1 has been reported many times." (PMID 37051625, 2023). "The 4 risk genes of LAMA4, POLA2, RAD51, and TYMS showed significant differences in the expression of normal and tumor tissues, and the 4 genes showed high expression in tumor tissues." (PMID 37051625, 2023). "Compared to the control group, inhibition of LAMA4 suppressed tumour growth, as indicated by a decrease in tumour weight, and accelerated cell apoptosis, as indicated by an increase in cleaved PARP." (PMID 36539799, 2022). "The present work shows that SOD3 triggers the transcription of the gene encoding laminin α4 (LAMA4) but represses that of the gene coding for laminin α5 (LAMA5) in ECs in vitro and in vivo, thus changing the laminin α4/laminin α5 ratio in tumor blood vessels." (PMID 35267534, 2022).